S100A12 (S100 calcium binding protein A12)
Description:
S100A12 is a calcium-, zinc- and copper-binding protein which plays a prominent role in the regulation of inflammatory processes and immune response. Its pro-inflammatory activity involves recruitment of leukocytes, promotion of cytokine and chemokine production, and regulation of leukocyte adhesion and migration. Acts as an alarmin or a danger associated molecular pattern (DAMP) molecule and stimulates innate immune cells via binding to receptor for advanced glycation endproducts (AGER). Binding to AGER activates the MAP-kinase and NF-kappa-B signaling pathways leading to production of pro-inflammatory cytokines and up-regulation of cell adhesion molecules ICAM1 and VCAM1. Acts as a monocyte and mast cell chemoattractant. Can stimulate mast cell degranulation and activation which generates chemokines, histamine and cytokines inducing further leukocyte recruitment to the sites of inflammation. Can inhibit the activity of matrix metalloproteinases; MMP2, MMP3 and MMP9 by chelating Zn(2+) from their active sites. Possesses filariacidal and filariastatic activity. Calcitermin possesses antifungal activity against C.albicans and is also active against E.coli and P.aeruginosa but not L.monocytogenes and S.aureus.
Synonyms: CAAF1; CAGC; MRP-6; p6; MRP6; CGRP; ENRAGE
Tractability: Small molecule: it has a high-quality binding pocket. Antibody: UniProt places it where antibodies can reach, with high confidence; its Gene Ontology location is reachable by antibodies, with high confidence. PROTAC: its protein half-life has been measured.
Gene: Protein-coding gene on chromosome 1 (153,373,711 to 153,375,621, reverse strand). Ensembl gene ENSG00000163221.
Subcellular location: Secreted; Cytoplasm; Cytoplasm, cytoskeleton; Cell membrane
Pathways (Reactome):
Immune System: Advanced glycosylation endproduct receptor signaling; Neutrophil degranulation; TAK1-dependent IKK and NF-kappa-B activation; TRAF6 mediated NF-kB activation
Gene Ontology:
Molecular function: identical protein binding; protein binding; RAGE receptor binding; calcium ion binding; calcium-dependent protein binding; copper ion binding; zinc ion binding
Biological process: antimicrobial humoral immune response mediated by antimicrobial peptide; defense response to fungus; killing of cells of another organism; positive regulation of canonical NF-kappaB signal transduction; xenobiotic metabolic process; defense response to bacterium; endothelial cell migration; inflammatory response; innate immune response; mast cell activation; monocyte chemotaxis; neutrophil chemotaxis; positive regulation of inflammatory response; positive regulation of MAP kinase activity
Cellular component: cytoplasm; nucleus; cytoskeleton; cytosol; extracellular region; plasma membrane; secretory granule lumen
Genetic constraint (gnomAD): Loss-of-function variants: 5 observed, 4.92 expected, observed/expected ratio (o/e) 1.02, 90% interval 0.52 to 1.82. That is too few expected variants to judge how well the gene tolerates losing a copy. Missense variants: 117 observed, 107.17 expected, observed/expected ratio (o/e) 1.09, 90% interval 0.94 to 1.27. Synonymous variants: 46 observed, 41.5 expected, observed/expected ratio (o/e) 1.11, 90% interval 0.87 to 1.42.
Homologues: Orthologues: chimpanzee S100A12 (98% identical), macaque S100A12 (87% identical), pig S100A12 (71% identical), rabbit S100A12 (67% identical), dog S100A12 (64% identical), zebrafish s100a10b (42% identical). Paralogues in human: S100A9 (47% identical), S100P (43% identical), S100Z (40% identical), S100A1 (38% identical), S100A8 (38% identical), S100A11 (36% identical), S100A5 (36% identical), S100B (36% identical), S100A2 (35% identical), S100A6 (35% identical), S100A4 (33% identical), S100A13 (32% identical), and 9 more.
Diseases named in the same sentence as S100A12 in open-access papers:
S100A12 is named in the same sentence as 288 diseases in open-access papers, as found by Europe PMC text mining. Sharing a sentence is not in itself a finding about the gene and the disease. The quoted sentences say what the papers report.
COVID-19 (53 papers, 2020 to 2026). A disease caused by infection with severe acute respiratory syndrome coronavirus 2. "In conclusion, calprotectin is associated with disease severity in COVID-19, and high levels reflect a neutrophil-driven inflammatory proteomic profile, particularly involving S100A12." (PMID 41683670, 2026). "Enzyme-linked immunosorbent assay was used to measure serum S100A12 levels in 63 patients with moderate COVID-19, 60 patients with severe disease and 33 healthy controls." (PMID 39066246, 2024). "The aim of this study was to evaluate serum S100A12 levels as a diagnostic and prognostic tool in COVID-19." (PMID 39066246, 2024). "Our study aimed to measure serum S100A12 levels in controls and patients with moderate and severe COVID-19 to assess associations with disease severity." (PMID 39066246, 2024). "The inflammatory mediator of EN-RAGE encoded by S100A12 was significantly correlated with COVID-19, and S100A8, S100A9, IRF3, IFI6, IFITM1, and IFITM3 have been reported to elicit autoinflammatory and autoimmune conditions in response to SARS-CoV-2 infection." (PMID 35172892, 2022). "Classical monocytes also transcribed several genes encoding for the S100 protein family, such as S100A4, S100A8, S100A9, and S100A12, which were recently implicated in COVID-19." (PMID 34424199, 2021). "Since S100A12 expression displayed a stepwise activation pattern and demonstrated strong association with severe COVID-19, it may serve as a good prognostic marker as well." (PMID 36649304, 2023). "Furthermore, two additional markers ApoA1 and S100A12, also showed diagnostic potential for COVID-19 confirming the earlier reported downregulation of ApoA1 and the upregulation of S100A12 in COVID-19 patients in France and China." (PMID 36590898, 2023). "Monocytes expressing high S100A12 and IL-8 are linked to COVID-19 severity." (PMID 34434199, 2021). "These transcriptomic profiles suggest that BALF FCN+ and FCN+SPP1+ macrophage clusters predominant in severe COVID-19 shared pathogenic molecular pathways, including the expression of their signature mediators S100A12 and SPP1 with ST CD48hiS100A12+ and CD48+SPP1+ clusters predominant in active RA." (PMID 34143756, 2021). "Therefore, S100A12 may serve as a novel biomarker for severe COVID-19 and an early diagnostic indicator for bacterial and viral infections." (PMID 39066246, 2024). "The consistent increase in ICAM1, MCL1, IL1β, and S100A12 expression in neutrophils from severe alive to severe dead patients underscores the critical role of neutrophils in COVID-19 severity." (PMID 39928675, 2025). "Transcriptomic analyses have shown overexpression of S100A8, S100A9, S100P and S100A12 in lung tissue from fatal COVID-19 patients." (PMID 41164170, 2025). "Serum S100A12 levels of moderate COVID-19 patients were higher in comparison to healthy controls and further increased in severe cases." (PMID 39066246, 2024). "In severe COVID-19, females tended to have lower serum S100A12 levels compared to males (p = 0.060)." (PMID 39066246, 2024). "S100A12, the gene encoding EN-RAGE, was analyzed in COVID-19 proteomic analysis of lung tissue from patients who had died, and it revealed a positive correlation between EN-RAGE abundance and inflammation severity." (PMID 38674681, 2024). "One study reported higher S100A12 levels in COVID-19 patients compared to healthy controls, with further increases in severe cases and a correlation with mortality." (PMID 39066246, 2024). "S100A12 protein levels were measured in the serum of 33 controls, 63 patients with moderate and 60 patients with severe COVID-19." (PMID 39066246, 2024). "In our investigation, we have identified significant transcriptomic alterations, particularly in the genes CD3, CD14, CD16, FOSB, S100A12, and TCRɣδ, that differentiate sepsis, mild COVID-19, septic shock, and severe COVID-19." (PMID 38892107, 2024).
COVID-19 (continued). "The neutrophil count was approximately 2-fold higher in severe compared to moderate COVID-19, while the increase in serum S100A12 was 1.5-fold, suggesting that S100A12 production by neutrophils is impaired in severe disease." (PMID 39066246, 2024). "Serum S100A12 positively correlated with neutrophils, basophils, monocytes, lymphocytes and immature granulocytes in patients with moderate COVID-19." (PMID 39066246, 2024). "Whole blood S100A12 expression in COVID-19 patients has been shown to correlate with disease severity and outcome." (PMID 39066246, 2024). "Serum S100A12 levels were elevated in moderate COVID-19 compared to controls and were even higher in severe cases." (PMID 39066246, 2024). "HSV reactivation in 20 patients with severe COVID-19 was related to higher serum S100A12 levels (p = 0.013)." (PMID 39066246, 2024). "al. described an increase in circulating S100A12 in COVID-19, which was even higher in severe cases." (PMID 39066246, 2024). "Transcriptomic analysis of whole blood and peripheral blood mononuclear cells from COVID-19 patients showed S100A12 activation primarily in severe cases." (PMID 39066246, 2024). "In this dataset, S100A12 expression was significantly different in the COVID-19 patient groups with different severity." (PMID 36649304, 2023). "When levels of host proteins were compared between COVID-19 and TB patients, five (ApoA1, CRP, ferritin, SAA1/A2, and S100A12) showed promising discriminatory potential as all but ApoA1 were significantly higher in COVID-19 patients’ sera." (PMID 36590898, 2023). "In this study, the activation patterns of this two-tiered innate immune response represented by IFI27 and S100A12 were explored based on 1421 samples from 17 transcriptome datasets derived from the blood of COVID-19 patients and relevant controls." (PMID 36649304, 2023). "Again, activation of S100A12 was generally accompanied by the activation of IFI27 in COVID-19 patients (84.1% for this cohort)." (PMID 36649304, 2023). "Similar with a previous report, classical monocytes displayed significantly higher levels of S100A family inflammatory genes (e.g., S100A12) in COVID-19 pediatric patients with relatively severe symptoms." (PMID 37848421, 2023). "For CRP, ferritin, SAA1/A2, and S100A12, serum cytokine levels were significantly higher in the COVID-19 group (p<0 · 0001, p = 0 · 0038, p<0 · 0001 and p<0 · 0001, respectively)." (PMID 36590898, 2023). "Among these proinflammatory cytokines, only S100A12, the gene encoding EN-RAGE, is substantially enhanced in the PBMCs of patients with COVID-19 patients, while its gene expression in PBMCs has been confirmed to be consistent with the protein level in plasma." (PMID 37932287, 2023). "As host markers for infection, activation of both IFI27 and S100A12 was observed in a significant portion of patients with COVID-19 compared to healthy controls." (PMID 36649304, 2023). "They found that S100A6, S100A9, and S100A12 were predictors of severe AP, and that a specific subtype of neutrophils was responsible for COVID-19-induced AP." (PMID 36830652, 2023). "Of note was that for six markers (CRP, ferritin, IL-6, IP-10, SAA1/A2, and S100A12) higher values were detected in COVID-19 sera whereas for ApoA1, significantly lower levels were detected in the COVID-19 group (p<0 · 0001)." (PMID 36590898, 2023). "It showed that activation of both genes can be observed in the first week of the disease course, and activation of IFI27 was more common and at larger scale than that of S100A12 in hospitalized patients with COVID-19." (PMID 36649304, 2023). "On the other hand, some of the top 26 genes identified from bulk RNA-seq data were also validated for their associated protein considerable abundances in the two proteomes, including the abundant S100A12 in either autopsy or severe/critical COVID-19 cases." (PMID 37936693, 2023). "Compared to the dataset GSE152641, activation of S100A12 was more common in patients with severe COVID-19." (PMID 36649304, 2023).
COVID-19 (continued). "C10 monocytes exhibited high expression of S100A family genes, including S100A8 and S100A12, along with low expression of HLA-DR, reminiscent of HLA-DRlowS100Ahigh monocytes in severe COVID-19." (PMID 37337301, 2023). "Thirdly, genes involving in neutrophil-mediated immunopathology (e.g., S100A8, S100A9 and S100A12, etc.)and pro-inflammatory responses were elevated in COVID-19 acute necrotizing encephalopathy patients." (PMID 37848421, 2023). "For example, S100A8, S100A9, and S100A12 levels in blood have recently been shown to correlate with disease severity in COVID-19 patients infected with SARS-CoV-250,51." (PMID 35396513, 2022). "All of the S100s (excluding S100A12) displayed significant sensitivity as predictive markers of symptomatic COVID-19, according to the ROC curve analysis of the Positive Asymptomatic and Positive Symptomatic group gene expression data." (PMID 35892571, 2022). "The shared key pathogenic macrophages were SPP1+ and S100A12+ clusters, and their signature SPP1 and S100A12 mediators were confirmed in COVID-19 cross-sectional and longitudinal patient plasma samples." (PMID 34143756, 2021). "We found that — in contrast, for example, to IL-6 — plasma SPP1 and S100A12 remained significantly higher than normal for at least 10 weeks after infection clearance in the post–COVID-19 convalescent phase." (PMID 34143756, 2021). "More specifically, 31 of the 62 hospitalized COVID-19 patients (50%) had S100A12 expression above the highest value in the control group." (PMID 34108608, 2021). "MMP8, MMP9, and S100A12, three genes that we found significantly upregulated in COVID-19 patient, are also common components in NETs, which further demonstrates the vital roles of NETs in COVID-19 development." (PMID 34457122, 2021). "The aim of this study is to investigate the potential of S100A12, a prominent marker gene for bacterial infection, in the prognosis of disease severity in COVID-19 patients." (PMID 34108608, 2021). "Patients with acute COVID-19 had significantly higher plasma levels of proinflammatory SPP1 and S100A12 than healthy donors and patients at the post–COVID-19 stage." (PMID 34143756, 2021). "Increased expressions of S100A8, S100A9, and S100A12 calgranulins found in the BALF fluid from COVID-19 patients indicate their potential role in generating the proinflammatory response." (PMID 33335518, 2020). "We found here that genes related to neutrophil activation, including S100A8, S100A9, and S100A12, were expressed at higher levels in monocytes from severe COVID-19 patients than those in mild cases." (PMID 33101705, 2020). "Serum S100A12 levels of controls were the lowest with 0.39 (0.06–1.51) μg/mL, were higher in moderate COVID-19 with 0.56 (0.02–6.81) μg/mL and with 0.83 (0.21–4.13) μg/mL were highest in severe COVID-19 patients." (PMID 39066246, 2024). "S100A12 expression was also elevated in the lung tissues of COVID-19 patients." (PMID 39066246, 2024). "Studies measuring circulating S100A12 in COVID-19 are sparse." (PMID 39066246, 2024). "If confirmed in larger studies, serological measurement of S100A12 could improve antibiotic and antiviral drug selection for COVID-19 patients." (PMID 39066246, 2024). "For S100A12, data on circulating levels in COVID-19 patients are scarce." (PMID 39066246, 2024). "This analysis identified serum S100A12 levels as a marker of severe COVID-19." (PMID 39066246, 2024). "Moreover, there were positive correlations of serum S100A12 with basophils, monocytes, lymphocytes and immature granulocytes in moderate COVID-19." (PMID 39066246, 2024). "Among the top 10 cytokines, S100A12, mainly secreted by the Mono_CD14 cell subset, may have a major role for initiating cytokine storms in COVID-19 acute necrotizing encephalopathy patients as this cytokine contributed to >96% of the cytokine score." (PMID 37848421, 2023). "A practical question is whether the activation of IFI27 or S100A12 is correlated with COVID-19 severity." (PMID 36649304, 2023).
COVID-19 (continued). "Interestingly, significantly elevated expression of the S100A12 gene was also seen in COVID-19 acute necrotizing encephalopathy patients." (PMID 37848421, 2023). "This trend of step-wise S100A12 activation in COVID-19 was replicated in two more datasets." (PMID 36649304, 2023). "In particular, we found an association between plasma proteins elevated in severe COVID-19, such as HGF, AREG, CKAP4, S100A12, NCF2, ITGB6, and a subpopulation of monocytes with lower expression of CD86 and HLA-DR, which are characteristics of myeloid-derived suppressor-like cells." (PMID 36829233, 2023). "The goal of this work is to find out whether IFI27 and S100A12 can be used as effective markers to monitor COVID-19 progression." (PMID 36649304, 2023). "Similarly, using a NUM score based on 7 host proteins (additionally including S100A12), COVID-19 patients were separated from healthy controls with sensitivity of 93% and specificity of 100%, respectively." (PMID 36590898, 2023). "Since S100A12 activation may last for several months in certain patients with COVID-19, it warrants further investigation whether this sustained activation is associated with some of the lingering symptoms in long COVID." (PMID 36649304, 2023). "Finally, correlation between S100A6, S100B, S100A8, S100A9, S100A12, and S100P and COVID-19 pathogenesis is discussed." (PMID 35892571, 2022). "More importantly, S100A12 expression at hospital admission was robustly correlated with future quantitative indexes of disease severity and outcome in COVID-19 patients, superior to established prognostic markers including CRP, PCT, d-dimer, ferritin, LDH and fibrinogen." (PMID 34108608, 2021). "More specifically, neutrophils which express high level of S100A12 could be heavily involved in host response to severe COVID-19 even at the early stage of the disease development, including both neutrophil expansion and neutrophil-related gene activation." (PMID 34108608, 2021). "Moreover, SPP1 and S100A12 each strongly correlated with the neutrophil/lymphocyte ratio, which itself is a prognostic biomarker for COVID-19 severity." (PMID 34143756, 2021). "We found that the S100A12 plasma levels were higher in COVID-19 patients categorized as severe compared with mild/moderate, and compared with those in convalescence, and with healthy donors, but comparable with the levels in patients with community acquired pneumonia." (PMID 34143756, 2021). "To validate the computational scRNAseq findings of shared pathogenic macrophage clusters in COVID-19 and RA, we quantified plasma concentrations of their key shared functional mediators SPP1 (osteopontin) and S100A12 (calgranulin C) in a cross-sectional comparison of additional patient groups." (PMID 34143756, 2021). "Also, the alarmin S100A12 exhibited heightened expression in granulocytes from severe COVID-19 patients." (PMID 33441124, 2021). "Plasma concentrations of SPP1 and S100A12 (key products of macrophage clusters shared with active RA) were high in severe COVID-19 and predicted the need for Intensive Care Unit transfer, and they remained high in the post–COVID-19 stage." (PMID 34143756, 2021). "In addition to these alterations in ISGs, both our data and theirs reveal an increase in markers that are associated with G-MDSC activation, including Arg1 and S100A12, indicating that activated Arg1+G-MDSC play a role in severe COVID-19." (PMID 34341659, 2021). "Besides, S100A12 is also found to herald worse cardiac output and mortality in pulmonary hypertension, which is also common in COVID-19." (PMID 34457122, 2021). "It is possible that patients with severe COVID-19 may activate pathways involving S100A12 in addition to the initial activation of interferon signaling pathways as a response to the overwhelming infection." (PMID 34108608, 2021).